PF4 (platelet factor 4)
Diseases named in the same sentence as PF4 in open-access papers (continued):
Sharing a sentence is not in itself a finding about the gene and the disease.
infection (96 papers, 2010 to 2026). The state of being infected such as from the introduction of a foreign agent such as serum, vaccine, antigenic substance or organism. "We have also shown that among pwCF, Pf4 carriage is associated with chronicity of Pa infection, older age, larger decreases in lung function during pulmonary exacerbation, and antibiotic resistance." (PMID 38275975, 2024). "Altogether, these data show that Pf4 phage variant infection results in complex network dysregulation, leading to reducing acute virulence in P. aeruginosa." (PMID 36036571, 2022). "We have previously shown that infection of P. aeruginosa PAO1 with a superinfective Pf4 variant abolished twitching motility and altered biofilm architecture." (PMID 36036571, 2022). "Here, we show that Pf4 variant infection results in a drastic dysregulation of 3,360 genes representing about 58% of P. aeruginosa genome; of these, 70% of the virulence factors encoding genes show a dysregulation." (PMID 36036571, 2022). "Consistent with its role, PF4 expression is raised after trauma to prevent blood loss from injury and also in response to infection." (PMID 34685765, 2021). "We show by confocal laser scanning microscopy that a Pf4 variant-infection altered P. aeruginosa H103 biofilm architecture either in static or dynamic conditions." (PMID 33143386, 2020). "This study aims to obtain further insights into the physiology of P. aeruginosa H103 (the PAO1 strain originating from Hancock’s laboratory after infection by a Pf4 filamentous phage variant, using combined phenotypic and gene expression analyses." (PMID 33143386, 2020). "Drastic phenotypes were observed in response to Pf4 variant infection at the cell-level, such as increased membrane fluidity related to SigX hyperactivity, and altered cell morphology." (PMID 33143386, 2020). "Experimental infection of PF4-deficient mice resulted in exacerbated lung inflammation, alveolar damage, and increased mortality." (PMID 29761104, 2018). "The post‐infectious subtype may result from the release of bacterial components, such as lipopolysaccharides, or host‐derived danger‐associated molecular patterns (DAMPs) during infection, which similarly interact with PF4 to initiate an immune response." (PMID 40589323, 2025). "In addition, higher expression of platelet factor 4 (PF4) on the circulating platelet-leukocyte aggregates of the protected animals was correlated with reduced infection risk." (PMID 38912579, 2024). "Accordingly, Pf4 variant infection (termed Pf4*) causes in vivo reduction of P. aeruginosa virulence and decreased production of N-acyl-homoserine lactones and 2-alkyl-4-quinolones quorum-sensing molecules and related virulence factors, such as pyocyanin, elastase, and pyoverdine." (PMID 36036571, 2022). "While there are clearly anti-infective activities of PF4, the PF4 species itself may also contribute to pathogenic infections." (PMID 33050376, 2020). "Herein, the response of P. aeruginosa H103 to Pf4 variant infection was investigated." (PMID 33143386, 2020). "In addition to these important observed cellular phenotypes, Pf4 variant infection resulted also in increased biofilm formation and c-di-GMP production, at least partly via the activity of both AlgU and SigX." (PMID 33143386, 2020). "In addition, Pf4 variant-infection resulted in cell envelope stress response, mostly mediated by the AlgU and SigX extracytoplasmic function sigma factors (ECFσ)." (PMID 33143386, 2020). "Indeed, in conditions of envelope alterations such as absence of oprF encoding the structural porin OprF or infection with the filamentous phage Pf4, biofilm formation was shown to be increased, as well as gene expression of cmpX, PA1181, cdrA, and pel, but not psl." (PMID 38544741, 2024).
infection (continued). "In this study, we show that the smallest protein encoded by Pf4, which we call PfsE (Pfsuperinfection exclusion), transiently inhibits T4P assembly through an interaction with the T4P platform protein PilC, providing resistance to further infection by T4P-dependent phages." (PMID 35038902, 2022). "Several lines of evidence now attest that autoantibodies against PF4 may arise under a large number of specific conditions, with several additional risk factors or associations, including disease, infection, and surgery, and as noted by a wide variety of researchers." (PMID 35225866, 2022). "In addition, Pf4 infection can lead to the emergence of small colony variants." (PMID 33143386, 2020). "Previous studies have revealed the presence of the DARC receptor in the erythrocytes of Bos taurus and Bos indicus, indicating that the administration of PF4 during an infection with Babesia spp." (PMID 39859202, 2025). "A potential mechanism for these subtypes is exposure of endogenous polyanionic molecules, such as glycosaminoglycans or DNA released during tissue injury or infection, which bind to PF4 and form immunogenic complexes." (PMID 40589323, 2025). "Stk11fl/fl × Pf4-Cre and control mice were infected with K. pneumoniae via the airways, and sacrificed 24 or 40 h after infection." (PMID 40332331, 2025). "At this post-infection timepoint, the expression levels of P-selectin and GPIIbIIIa were not different from those in naïve mice, and similar in Stk11fl/fl × Pf4-Cre and control mice." (PMID 40332331, 2025). "PF4 has been shown to regulate infections by various viruses, including human immunodeficiency virus type I (HIV-1), respiratory syncytial virus (RSV), H1N1 influenza, dengue virus, and Japanese encephalitis virus (22, –, 26)." (PMID 39772852, 2025). "So, it is quite explicable why important amounts of PF4 are released from activated platelets, in infection." (PMID 38792336, 2024). "Altogether, the data suggest that in UM, processes such as NETosis (MPO and cfDNA) and active coagulation (D-dimers) are early events in infection that correspond to elevated anti–PF4/P IgG levels." (PMID 38652559, 2024). "We sought to investigate the transcriptional responses of BCs under conditions that emulate infection with Pa and exposure to high Pf4 burden." (PMID 38275975, 2024). "PF4 levels tend to be elevated when platelet activity is triggered by avascularization or infection." (PMID 39189244, 2024). "Collectively, these results indicate that Pf4 transfer can occur in polymicrobial and infection conditions." (PMID 38365255, 2024). "Previous murine vaccination studies demonstrated that a humoral immune response against the Pf4 phage results in protection against Pa and clearance of infection in a murine wound infection model." (PMID 38400099, 2024). "Creating a safe and effective vaccine that can mount a robust immune response against Pf4 phage is an important advancement towards the development and clinical testing of phage-based vaccines targeting multi-drug-resistant Pa infections." (PMID 38400099, 2024). "By contrast, infection by P. aeruginosa strains with Pf4 superinfection resulted in enhanced survival within 72 h, indicating a lower level of pathogenesis." (PMID 39052320, 2024). "At sites of infection, Pf4 virions are internalized by immune cells via endocytosis, where they activate Toll-Like receptor (TLR) 3 signaling, leading to the production of type I interferons while also reducing TNF-α production." (PMID 38400099, 2024). "Anti-PF4 antibodies can also be detected in patients with mild and severe COVID-19 infection, and they are correlated with infection severity." (PMID 40729266, 2024). "Platelet factor 4 is a platelet kinocidin that is released abundantly during the time of infection, while platelet-viral interaction occurs, and this platelet factor 4 is responsible for inhibiting the broad spectrum of HIV-1." (PMID 36891250, 2023).
infection (continued). "This strain was shown to protect zebrafish larvae against V. anguillarum PF4 infection by preventing the expression of inflammatory cytokines IL1β and TNFα." (PMID 36836388, 2023). "Pf4 virions promote biofilm formation, protect bacteria from antibiotics, and modulate animal immune responses in ways that promote infection." (PMID 36800381, 2023). "Prior work demonstrates that Pf4 enhances P. aeruginosa PAO1 virulence potential in mouse models of infection by modulating innate immune responses." (PMID 36800381, 2023). "The infection of Pf4 phages in different P. aeruginosa strains resulted in a larger amount of formed biofilm." (PMID 35746731, 2022). "While the ΔintF4 mutant phage titer was equal to wild-type Pf4, the ΔintF4/pfsE mutant phage was approximately 1,000-fold more infective, indicating that pfsE restricts Pf4 infection and thereby protects the bacterial host from lysis." (PMID 35038902, 2022). "Upon the phage Pf4 infection, a slight increase in hydrophobicity in both examined lysogenic strains was observed, similar to findings for Ralstonia phage φRSS1." (PMID 35746731, 2022). "The infection with Pf4 reduced twitching motility, with statistically significant difference, only for Pf4-infected PA14 (p < 0.05)." (PMID 35746731, 2022). "This possibility is consistent with our previous work demonstrating that Pf4 superinfection promotes a noninvasive infection phenotype in vivo." (PMID 35038902, 2022). "It was observed that Covid-19 patients present with high levels of anti-PF4/heparin antibodies in the context of the infection, resulting in reduced specificity of this parameter for the detection of HIT with frequent false positive test results." (PMID 36163073, 2022). "Namely, upon Pf4 infection, both LESB58 and PA14 strains changed autoaggregation ability from moderately aggregative to non-aggregative (p < 0.001 and 0.0001, respectively)." (PMID 35746731, 2022). "In these strains, Pf4 can establish a chronic productive infection with integration into the host genome, and expression of Pf4 genes can exceed expression of indigenous filamentous prophages." (PMID 35746731, 2022). "PA0721 is a small 30 residue uncharacterized protein, and PA0724 is the Pf4 minor coat protein CoaA, which is involved in receptor binding during the initial steps of infection." (PMID 35038902, 2022). "In the monocultures using M9-CAA and M9-casein media, we tested the infection capacity of Pf4 and ZCO1 phages on the WT, ΔCRISPR, and ΔlasRrhlR strains." (PMID 35699339, 2022). "Among the genes up-regulated in convalescent samples compared to pre-infection was platelet factor 4 (PF4)." (PMID 36522333, 2022). "In summary, the results clearly indicate that Pf4 can be induced by subinhibitory concentrations of certain antimicrobial agents or by infection by obligatory lytic phages, and can successfully infect other strains." (PMID 35746731, 2022). "The infection with Pf4 increased LESB58 sensitivity to ciprofloxacin, gentamicin, ceftazidime, tetracycline, and streptomycin, and PA14 to ciprofloxacin and ceftazidime." (PMID 35746731, 2022). "The presence of Pf4 RF in these strains, as well as in the isolated viral DNA, indicates that this phage established a chronic productive infection in the given strains." (PMID 35746731, 2022). "The infection with Pf4 filamentous phages can contribute to the increased antibiotic susceptibility of bacteria, and the phenomenon seems to be both strain- and antibiotic-dependent." (PMID 35746731, 2022). "Induction of Pf4 from the original host PAO1 was also examined upon infection by obligatory lytic phage JG024, by examining expression of the same genes as for antibiotics." (PMID 35746731, 2022). "Except for Pf4 infection capacity in M9-CAA, the phage infection capacity in the ΔCRISPR strains was higher than the WT (WT/ΔCRISPR in M9-CAA and ZCO1, P = 0.0011)." (PMID 35699339, 2022).
infection (continued). "The finding that susceptibility is increased for various antibiotics, however, supports the assumption that Pf4 phage changes cell permeability upon infection." (PMID 35746731, 2022). "Detecting coaA gene expression and RF presence in bacterial DNA by qRT-PCR, it was confirmed that both indigenous prophages, Pf5 from PA14 or PfLES58 from LESB58, are still produced upon infection with Pf4." (PMID 35746731, 2022). "Further investigations are therefore required to understand the mechanisms employed by the CRISPR-Cas and QS systems in defending against Pf4 infection." (PMID 35699339, 2022). "Collectively, these phenotypes help explain why in P. aeruginosa PAO1 deleting the Pf4 prophage from the chromosome reduces bacterial virulence in murine lung and wound infection models." (PMID 35038902, 2022). "The cured strain infection with Pf4 phages, extracted from WT PAO1, resulted in plaque formation and bacterial susceptibility, unlike the WT strain." (PMID 33670076, 2021). "Central to these effects of the Pf4 phage in P. aeruginosa is the repressor protein, Pf4r, which not only controls immunity to infection and phage replication but also acts to regulate the expression of host genes." (PMID 34452479, 2021). "For instance, it was determined by qPCR method that only three Pf4 particles were produced per 10,000 cells in the lungs of mice after 48 h of infection." (PMID 35095778, 2021). "This feature is in agreement with the diminished innate immunity observed in the PF4 KO mice during early infections." (PMID 34685765, 2021). "This feature is consistent with the reduced innate immunity observed in the PF4 KO mice during early infections." (PMID 33050376, 2020). "Unexpectedly, a significant amount of PF4 is also released by activated platelets in response to infection." (PMID 33050376, 2020). "These specific microparticles bind to polyanionic sequences on the surface of aerobic bacteria, giving rise to an antigenic complex that induces the early formation of IgG-IgA-IgM against PF4-GAGs as an innate immune response to infection." (PMID 32846949, 2020). "Although a major physiological function of PF4 is to promote blood coagulation, this cytokine is involved in innate and adaptive immunity in events when platelets are activated in response to infections." (PMID 33050376, 2020). "Studies have proven that platelets protect the host during erythrocytes infection by releasing platelet factor 4 (PF4) molecules which has plasmocidal activity." (PMID 32268918, 2020). "More specifically, Pf4 can promote bacterial adhesion to mucin, alter progression of the inflammatory response, and contribute to noninvasive infection in a murine pneumonia model." (PMID 30475408, 2019). "The results showed that the WSSV levels were significantly decreased by PF4 at different concentrations in shrimp infected with WSSV at 12 h to 24 h post-infection compared with the controls." (PMID 27631372, 2016). "Platelet-derived chemokines such as RANTES (CCL5) and platelet factor 4 (CXCL4, PF4) are well-known molecules responsible for neutrophil recruitment to sites of inflammation/infection." (PMID 27458459, 2016). "WT and PF4−/− mice were infected and on day 5 post infection brain mononuclear cells were isolated as we have described and the total number of monocytes quantified using a mouse automated hematologic analyzer." (PMID 20454664, 2010). "Moreover, we found that PF4 substantially modified Ad5 attachment and infection levels in numerous immortalized or primary cell types." (PMID 41509905, 2026). "Therefore, clinical evaluation, laboratory testing and possible ‘triggers’ (i.e., infection, surgery or adenovirus vaccination) must be taken into account when diagnosing anti‐PF4 disorders." (PMID 40589323, 2025). "The Pf4 uses the type IV pili of P. aeruginosa as a surface receptor for infection." (PMID 38365255, 2024).
infection (continued). "Similarly, anti-PF4/P antibodies are produced from rapidly responding marginal zone B cells through TLR signaling in response to blood infections when antigen is presented via complement." (PMID 38652559, 2024). "In addition to clotting-specific functions, PF4 also seems to be involved in immune functioning, with its secretion and serum levels increasing during infection – which is expected as platelet activation increases in response to infection." (PMID 39014464, 2024). "We further tested whether Pf4 transfer could occur during infection in mice using a lung infection model." (PMID 38365255, 2024). "In vivo, this could result in reduced biofilm integrity, enhanced recognition and clearance of Pa harboring Pf4, and give the host a chance to clear the infection before a biofilm can be established." (PMID 38400099, 2024). "Additionally, during infection, platelets bind to iRBCs, deploying PF4, which accumulates and destroys the parasite within the erythrocyte." (PMID 38652559, 2024). "The Pf4 filaments not only contribute to biofilms as structural components but also act as an iron chelator and inhibitor of fungal growth, a physical barrier against antibiotics, and an important immune modulator during infection." (PMID 38365255, 2024). "Since Pf4 is actively extruded by Pa and is highly abundant in the lungs of some pwCF, we believe that this finding identifies a novel and previously unsuspected mechanism involved in the pathogenicity of chronic Pa infections in the CF airway." (PMID 38275975, 2024). "Furthermore, strains cured of their Pf4 infection (ΔPf4) are less virulent in animal models of infection." (PMID 36800381, 2023). "Nevertheless, PF4 may trigger an antibody-mediated immune response against bacteria at later stages of infection, as previously suggested." (PMID 37868353, 2023). "A preceding exposure to one infectious agent could induce the rapid generation of anti-PF4 IgG antibodies from preformed B-cells during infection with another bacterial species, as a result of an interaction between PF4 with the second infectious agent." (PMID 37834770, 2023). "Further studies are required to determine whether PF4 is protective in other infection models and with other pathogens." (PMID 37868353, 2023). "Moreover, LESB58 changed sensitivity to streptomycin upon Pf4 infection from intermediately sensitive to sensitive, while in PA14, this change was from resistant to intermediate resistant." (PMID 35746731, 2022). "Also, the Pf4 phage density following infection of the ΔCRISPR strain increased significantly compared to the WT (t = 7.04, df = 8, P < 0.0001)." (PMID 35699339, 2022). "Finally, Pf4 infection can re-sensitize newly infected strains to antibiotics, which potentially has great therapeutic implications." (PMID 35746731, 2022). "Moreover, for the first time, we proved that the infection of PAO1 with obligate lytic phage JG024 at MOI 0.25 can affect the expression of Pf4 prophage key genes up to 24 h after infection." (PMID 35746731, 2022). "The higher amounts of plasma PF4/CXCL4 detected in few of our N-PV patients might be showing the early stages of PF4/CXCL4 response to the infection." (PMID 34991449, 2022). "Finally, original LESB58 was intermediately sensitive to tetracycline, and became sensitive upon Pf4 infection." (PMID 35746731, 2022). "Infection by Pf4 phages severely inhibited pyocyanin production of lysogenic strains." (PMID 35746731, 2022). "Furthermore, CXCL4 (PF-4) can mediate T-cell trafficking to sites of injury or infection by direct and indirect stimulation of CXCR3 expression on T cells." (PMID 35406684, 2022). "Mediators released by activated platelets in response to infection, such as antimicrobial peptides, high mobility group box 1 protein, platelet factor 4 (PF4), and PF4+ extracellular vesicles promote neutrophil activation, resulting in the release of neutrophil extracellular traps and histones." (PMID 35874830, 2022).